SCN10A (sodium voltage-gated channel alpha subunit 10)
Diseases named in the same sentence as SCN10A in open-access papers (continued):
Sharing a sentence is not in itself a finding about the gene and the disease.
Ventricular arrhythmia (5 papers, 2021 to 2025). "Therefore, the observed improved survival of SCN10A−/−/CaMKIIδc+/T-animals is associated with reduced ventricular arrhythmias." (PMID 34782600, 2021). "While there was no change with respect to HF progression, i.e., similar left ventricular ejection fraction and chamber diameters, we found reduced ventricular arrhythmias and an improved animal survival of SCN10A−/−/CaMKIIδc+/T animals." (PMID 34782600, 2021). "Likewise, we observed less ventricular arrhythmias in SCN10A−/−/CaMKIIδc+/T mice in vivo." (PMID 34782600, 2021). "In conclusion, SCN10A/NaV1.8 is detectible in canine GPs but not in ventricles, and blockade of NaV1.8 in cardiac GPs increases the incidence of ventricular arrhythmias in AMI hearts." (PMID 34409080, 2021). "While SCN10A/NaV1.8 is detectible in canine GPs but not in ventricles, blockade of NaV1.8 in GP increases the incidence of ventricular arrhythmias in AMI hearts." (PMID 34409080, 2021). "For ventricular arrhythmia, many of the significant proteins identified by the diffusion algorithm are ion channel proteins, such as those that contribute to Ca2+ (CACNA1C, CACNA1C-IT2), Na+ (SCN3A, SCN1B, SCN4B, SCN10A), or K+ (KCNQ1, KCNE3, KCNH2) transport in the heart." (PMID 39954672, 2025).
heart failure (4 papers, 2019 to 2025). Inability of the heart to pump blood at an adequate rate to meet tissue metabolic requirements. "Moreover, in a chronic CaMKIIδc overexpression heart failure mouse model, genetic ablation of SCN10A significantly suppressed INa,L, reduced Ca2+-dependent proarrhythmic triggers and delayed afterdepolarizations in ventricular myocytes, and decreased in vivo arrhythmia events." (PMID 40182425, 2025). "Recently, increased SCN10A/NaV1.8 expression in human ventricular tissue isolated from heart failure and hypertrophic patients as compared to non-failing and healthy myocardium, has been demonstrated." (PMID 31916131, 2019).
long QT syndrome (4 papers, 2020 to 2023). "PVs and LPVs in the ABCC9, AKAP9, ANK2, and SCN10A have been implicated in conduction defects and arrhythmias, particularly the long QT syndromes and conduction defects." (PMID 34790974, 2021).
multiple sclerosis (4 papers, 2015 to 2023). A progressive autoimmune disorder affecting the central nervous system resulting in demyelination. "P2X purinoceptor 1, encoded by P2rx1, potentiates neurite outgrowth, while mutations in sodium voltage-gated channel alpha subunit 10, encoded by Scn10a, has been implicated in neurological disorders like multiple sclerosis and Pitt-Hopkins." (PMID 32582210, 2020). "For instance, hereditary demyelinating neuropathy leads to an upregulation of Scn10a/Nav1.8 and abnormal axonal excitability, and ectopic Scn10a/Nav1.8 is observed in the cerebellum of the experimental autoimmune encephalomyelitis (EAE) mouse model of multiple sclerosis (MS) and in MS patients." (PMID 36224259, 2023).
left ventricular hypertrophy (3 papers, 2019 to 2024). Enlargement of the LEFT VENTRICLE of the heart. "Interestingly, variants significantly associated with PR interval were mainly located over SCN10A, whereas variants associated with QRS duration in left ventricular hypertrophy were distributed over SCN5A and SCN10A." (PMID 31666509, 2019).
myocardial infarction (3 papers, 2016 to 2025). Gross necrosis of the myocardium, as a result of interruption of the blood supply to the area, as in coronary thrombosis. "Retrospectively, SCN10A common variant identified in the BrS GWAS study have been also associated with the risk of VF in the context of myocardial infarction and with the pacemaker implantation rate." (PMID 27200363, 2016). "SCN10A/NaV1.8 may be associated with a lower risk of ventricular fibrillation in the setting of acute myocardial infarction (AMI), but if and by which mechanism NaV1.8 impacts on ventricular electrophysiology is still a matter of debate." (PMID 34409080, 2021).
ventricular fibrillation (3 papers, 2013 to 2021). A disorder characterized by an electrocardiographic finding of a rapid grossly irregular ventricular rhythm with marked variability in QRS cycle length, morphology, and amplitude. "DNA variation within SCN10A has been associated with abnormalities of cardiac ventricular depolarization, conduction, and ventricular fibrillation." (PMID 23593153, 2013).
Anorexia (2 papers, 2021 to 2025). Lack of desire to eat (loss of appetite). "Additionally, the administration of the SCN10A antagonist (A‐803467) effectively mitigated DON‐induced anorexia and aversive‐like emotions, highlighting the pivotal role of the PVT‐CeA circuit and CeAGABA neurons in regulating the physiological and emotional impacts of DON." (PMID 40019402, 2025). "Utilizing the Scn10A antagonist, A‐803467, was observed to effectively counteract DON‐induced anorexia and aversive‐like emotions, offering a promising therapeutic pathway." (PMID 40019402, 2025).
cardiac arrest (2 papers, 2020 to 2024). Cessation of breathing and/or cardiac function. "Previous GWAS highlighted the significance of genetic variations in SCN10A on cardiac conduction, a factor associated with unanticipated cardiac arrest." (PMID 38750426, 2024).
erythromelalgia (2 papers, 2016 to 2025). A rare neurovascular peripheral pain disorder due to the intermittent blockage of the blood vessels, usually in the lower extremities or hands. "Recently, rare variants of genes other than SCN9a were described in patients with clinically verified erythromelalgia: those genes included SCN10A (Nav1.8), SCN11A (Nav1.9), SCN5A (Nav1.5), SCN7A (Nav2.1), SCN8A (Nav1.6), SCN1B (Nav β1 subunit), SCN3B (Nav β3 subunit), TRPA1, TRPV1, WNK1 and NGFR." (PMID 27598514, 2016).
hypertrophic cardiomyopathy (2 papers, 2021 to 2024). A condition in which the myocardium is hypertrophied without an obvious cause. "CACNA1D, MYH6 and SCN10A had a cardiovascular disease as their top disease association (sinoatrial node dysfunction, hypertrophic cardiomyopathy and AF, respectively)." (PMID 38969939, 2024). "In addition, genetic variations in SCN10A have been associated with cardiac conduction abnormalities in hypertrophic cardiomyopathy patients and with GI toxicity in taxane-treated patients." (PMID 33578652, 2021).
inflammatory bowel disease (2 papers, 2018 to 2025). A spectrum of small and large bowel inflammatory diseases of unknown etiology. "For example, in patients suffering inflammatory bowel disease, the SNP of rs6795970 for SCN10A is significantly prevalent in patients with hypoalgesic inflammatory bowel disease, suggesting a link between the genetic mutation of Nav1.8 and visceral pain." (PMID 40427587, 2025).
ovarian carcinoma (2 papers, 2020 to 2021). A malignant neoplasm originating from the surface ovarian epithelium. "Across histologic subtypes of ovarian cancer, most VGSC were expressed, except SCN10A." (PMID 34771603, 2021).
autonomic dysfunction (1 paper, 2023). "The voltage-gated sodium channel NaV1.8 is prominently expressed in the soma and axons of small-caliber sensory neurons, and pathogenic variants of the corresponding gene SCN10A are associated with peripheral pain and autonomic dysfunction." (PMID 37695396, 2023).
behavioral disorders (1 paper, 2020). "Another cluster, consisting of three genes (CHD2, SCN10A, and TBC1D8), was associated with cellular assembly and organization, nervous system development and function, and ion channels, as well as neurological disease, skeletal and muscular disorders, and behavioral disorders." (PMID 33584793, 2020).
COVID-19 (1 paper, 2024). A disease caused by infection with severe acute respiratory syndrome coronavirus 2. "The significance of SCN10A has thus been assessed in both pulmonary and cardiac disorders, in accordance with recognized risk factors for severe COVID-19." (PMID 38750426, 2024).
dilated cardiomyopathy (1 paper, 2021). Cardiomyopathy which is characterized by dilation and contractile dysfunction of the left and right ventricles. "In fact, we observed an improved survival in these SCN10A−/−/CaMKIIδc+/T mice but still with an unchanged typical phenotype of dilated cardiomyopathy in these blinded investigations." (PMID 34782600, 2021).
Fever (1 paper, 2025). Body temperature elevated above the normal range. "Hyperthermia exacerbated the BrS phenotype in hiPSC-CMs carrying SCN10A and SCN5A variants, whereas LPS aggravated the phenotype in all three BrS variants through distinct mechanisms; Hyperthermia and LPS effects on BrS phenotype may be genotype-dependent." (PMID 41327470, 2025).
gastroparesis (1 paper, 2023). Paralysis of the muscles of the stomach wall resulting in delayed emptying of the gastric contents into the small intestine. "Another SCN10A loss-of-function variant (p.D1639N) was identified in a patient suffering from diffuse pain and gastroparesis and was shown to impair the trafficking of NaV1.8 to the cell surface." (PMID 37695396, 2023).
homeostasis (1 paper, 2023). "However, the combined heterozygous RYR2-A1855D and SCN10A-Q1362H variants in the proband iPS-CMs resulted in accentuated Ca2+ homeostasis disorders, action potential prolongation and susceptibility to early afterdepolarizations at high stimulus frequencies." (PMID 37122207, 2023).
Intellectual disability (1 paper, 2022). "In this proband we identified a biallelic truncating variant in the gene SCN10A, encoding the voltage-gated sodium channel subunit alpha Nav1.8, that is a likely cause of his ASD and intellectual disability." (PMID 36140801, 2022).
myoclonic epilepsy (1 paper, 2020). A group of epilepsy syndromes in which myoclonic seizures are a prominent feature. "GPR98, a gene implicated in myoclonic epilepsy, showed the highest overrepresentation of variants in severe patients in three categories of variants, and SCN10A, another sodium channel alpha‐subunit gene, was most often implicated in mild patients." (PMID 32032478, 2020).
psychosis (1 paper, 2025). "SCN10A plays a critical role in neuronal excitability and pain perception, but no direct evidence currently links it to childhood trauma or psychosis." (PMID 41333685, 2025).
Sinus bradycardia (1 paper, 2024). Bradycardia related to a mean resting sinus rate of less than 50 beats per minute. "Scn10a has been associated with sinus bradycardia phenotype and irregular RR interval upon scruffing." (PMID 38228144, 2024).
ventricular tachycardia (1 paper, 2021). A disorder characterized by an electrocardiographic finding of three or more consecutive complexes of ventricular origin with a rate greater than a certain threshold (100 or 120 beats per minute are commonly used). "Most importantly, the incidence of ventricular tachycardia (VT) was significantly lower (91%) in SCN10A−/−/CaMKIIδc+/T." (PMID 34782600, 2021).
cancer (20 papers, 2010 to 2025). A tumor composed of atypical neoplastic, often pleomorphic cells that invade other tissues. "Out of these SNPs, several occur in genes associated with behavior (Scn10A), metabolism (Ppgca1b), cancer (Brca2), and immune response (Map3k1, OAS2, IL18R1)." (PMID 21668978, 2011). "We found a significant locus adjacent to sodium voltage-gated channel alpha subunit 10 (SCN10A), and a borderline significant locus adjacent to cancer susceptibility 20 (CASC20)." (PMID 38918595, 2024). "Except SCN10A, other genes have been verified to be related to carcinogenesis or cancer progression." (PMID 34923986, 2021). "Secondly, the mechanisms underlying the downregulation of SCN5A and upregulation of SCN10A as well as the reduced methylation of IKs gene by cancer cell secretions were not revealed." (PMID 35265687, 2022). "The protein levels of SCN5A and KCND3 decreased and SCN10A and KCNQ1 increased, similar to the levels in AGS and SW480 cancer cell media treated cells." (PMID 35265687, 2022). "Predicted interaction between SACS or SCN10A proteins and chemotherapy drugs, cyclophosphamide/piroxicam, was exhibited in the present study via several cytochrome P450 (CYP) proteins which plays an important role in cancer development and response to therapy." (PMID 30001383, 2018).
peripheral neuropathy (16 papers, 2014 to 2025). A disorder affecting the peripheral nervous system. "For the groups of functionally validated voltage-gated sodium channel variants, a significant association of SCN10A with small fibre neuropathy in Europeans was found." (PMID 36895957, 2023). "Two participants diagnosed with small fibre neuropathy carried likely pathogenic variants, SCN10A p.Gly1662Ser and SCN11A p.Cys1543Tyr." (PMID 36895957, 2023). "Several pathogenic or likely pathogenic missense variants in SCN10A have been linked to peripheral neuropathies characterized by recurrent pain episodes and itching in distal body parts, predominantly involving the feet and lower legs." (PMID 37695396, 2023). "Among various predisposing conditions, mutations in the SCN9A and SCN10A genes are often related to the development of small-fibre neuropathy." (PMID 36558965, 2022). "In humans, loss-of-function mutations in SCN9A, the gene encoding NaV1.7, leads to congenital insensitivity to pain, while several gain-of-function mutations in SCN9A and SCN10A (the gene encoding NaV1.8) are associated with painful peripheral neuropathies." (PMID 32092883, 2020). "Gene alterations, such as GSTP1 and GSTM1, glutathione-S-transferase genes and voltage-gated sodium channel genes SCN4A, SCN9A and SCN10A, together with pre-existing peripheral neuropathy have been demonstrated to be the principal risk factors for OIPN onset." (PMID 33671327, 2021).
cardiovascular disease (3 papers, 2022 to 2024). "SCN10A has been linked to 51 cardiovascular disorders and shares an EH-associated SNP with SCN5A according to our GWAS analysis (rs1391189881 with log-p value ≥ 3) (Supplementary S4 and S6)." (PMID 35629146, 2022).
neurological disorders (3 papers, 2020 to 2024). "Of note, previous evidence showed that the expression of HCN1 and SCN10A exhibit sex differences in several nerve tissues, which might contribute the different prevalence of neurological disorders." (PMID 38289829, 2024).
cardiac disease (2 papers, 2020 to 2023). "For example, while CDK13, CHD4, KDM5A, and SCN10A are related to familial heart disease, CFH, DGUOK, and POLE are related to familial vascular disease." (PMID 31941532, 2020).
SCN10A also shares sentences with these, for which no sentence is quoted: neuropathic pain (15 papers); diabetes (10); cardiac arrhythmias (9); peripheral nerve injury (8); bone cancer (7); neuroma (7); painful (7); tumor (6); colitis (5); diabetic neuropathy (5); infection (5); osteoarthritis (5); Bradycardia (3); cardiac hypertrophy (3); cardiomyopathy (3); ciguatera (3); inflammation (3); migraine (3); neuroblastoma (3); Pitt-Hopkins syndrome (3); apical periodontitis (2); asthma (2); autism spectrum disorder (2); breast carcinoma (2); complex regional pain syndrome (2); dry eye (2); experimental autoimmune encephalomyelitis (2); fibromyalgia (2); injury (2); metabolic disease (2).
A further 49 diseases each share a sentence with SCN10A in 2 papers or fewer.